LECT2 (leukocyte cell derived chemotaxin 2)
Diseases named in the same sentence as LECT2 in open-access papers (continued):
Sharing a sentence is not in itself a finding about the gene and the disease.
cancer (14 papers, 2016 to 2024). A tumor composed of atypical neoplastic, often pleomorphic cells that invade other tissues. "A large number of studies have now shown that LECT2 is associated with the progression of a variety of cancers." (PMID 36160006, 2022). "Changing levels of LECT2 have been implicated in multiple human disease states, including cancers." (PMID 38177412, 2024). "Indeed, we provided evidence that loss of Lect2 substantially impairs the therapeutic efficacy of checkpoint blockade in cancer immunotherapy for murine ID8 EOC, which suggests that loss of Lect2 poses a significant obstacle to EOC immune therapy." (PMID 38177412, 2024). "The results showed that LECT2 expression was negatively correlated with immune infiltration of B cells, Neutrophil, Monocyte, Cancer-associated fibroblast, and Myeloid dendritic cell, and positively correlated with T cell CD8+ naive, Endothelial cell, and Hematopoietic stem cell." (PMID 36160006, 2022). "All of this evidence suggests that LECT2 is closely associated with immune cell infiltration and may serve as a promising target for cancer immunotherapy." (PMID 36160006, 2022). "Additionally, the results showed that LECT2 expression was negatively correlated with immune infiltration of B cells, Neutrophil, Monocyte, Cancer-associated fibroblast, and Myeloid dendritic cell, and positively correlated with T cell CD8+ naive, Endothelial cell, and Hematopoietic stem cell." (PMID 36160006, 2022). "Satoshi Yamagoe, Toshinari Takamura, and Shuichi Kaneko collaborated to uncover the therapeutic potential of LECT2 in treating infectious diseases and cancer." (PMID 38881894, 2024). "The Western blot and immunohistochemical staining demonstrated that the phosphorylated c-Met levels were higher in cancer obtained from Lect2−/− mice than Lect2+/+ or Lect2+/- mice." (PMID 38177412, 2024). "Meanwhile, we ranked the expression levels of LECT2 in 33 cancers and found that LECT2 had higher expression levels only in HCC and CHOL." (PMID 36160006, 2022). "In our further research, the effect of LECT2 on cancer immune should be investigated in this immune-competent orthotopic HCC model." (PMID 36055405, 2022). "Because LECT2 is expressed only at high levels in CHOL and HCC and is too low in other cancers, we focused on the prognostic value of LECT2 in CHOL and HCC." (PMID 36160006, 2022). "Compared with the normal tissues, the results showed that LECT2 was differentially expressed in 14 of the 33 cancers (BLCA、BRCA、CHOL、ESCA、GBM、HNSC、KICH、KIRC、HCC、LUAD、LUSC、PCPG、PRAD、UCES)." (PMID 36160006, 2022). "To comprehensively analyze the mutational, CNV, and methylation spectrum of LECT2, we used DriverDBv3 to explore the mutational and CNV in all cancer types in the TCGA database." (PMID 36160006, 2022). "At the same time, the GSEA pathway enrichment analysis showed that the JAK/STAT signaling pathway, cell cycle, and pathways in cancer were enriched in the low LECT2 expression group." (PMID 36160006, 2022). "As EMT is considered to be a fundamental process involved in cancer metastasis, the role of LECT2 in migration and invasion was thus investigated." (PMID 33937262, 2021). "The dataset of this article presented new original data about the effect of lamprey LECT2 on cancer cells migration and macrophages phagocytosis." (PMID 29845097, 2018). "We further investigated whether Lect2 possesses immunostimulatory properties and suppresses cancer-promoting inflammation of EOC using a syngeneic ID8 mouse model." (PMID 38177412, 2024). "Loss of Lect2 fosters the accumulation/activation of M-MDSC, leading to the presence of M2-like TAMs and pro-tumorigenic cytokines (IL-4, IL-6, IL-10, and TGF-β) that can impair the activity of T cells in the fight against cancer." (PMID 38177412, 2024). "Targeting LECT2 could potentially hold therapeutic significance in the context of infectious diseases and cancer." (PMID 38155961, 2023).
cancer (continued). "All the results show that LECT2 is a potential anti-tumor cytokine for cancer therapy." (PMID 36969200, 2023). "Together, LECT2 may antagonize β-catenin signaling, thereby suppressing cancer stemness/EMT/angiogenesis in HCC." (PMID 36055405, 2022). "We further analyzed the prognostic value of LECT2 in cancers with differential expression." (PMID 36160006, 2022). "It has been reported that LECT2 acts as a potent antagonist of c-MET signaling in many cancer types Thus, we investigated whether exogenous LECT2 affected the c-MET signaling in HCC cells." (PMID 36055405, 2022). "We analyzed the expression levels of LECT2 in 33 cancers in the TCGA database." (PMID 36160006, 2022). "Our findings reveal previously unrecognized crosstalk between MET-mediated proliferation and innate immunity and suggest that targeting LECT2 may have therapeutic value in infectious diseases and cancer." (PMID 35676290, 2022). "However, the pathologic role of LECT2 in other cancer types is unclear and left largely unexplored." (PMID 38177412, 2024). "The expression of LECT2 has been shown to demonstrate a negative correlation with the immune infiltration of B cells, neutrophils, monocytes, cancer-associated fibroblasts, and myeloid DCs, while exhibiting a positive correlation with T cells, endothelial cells, and hematopoietic stem cells." (PMID 38155961, 2023). "Thus, we employed the immunoblot analysis to delineate whether LECT2-modulated cancer stemness/EMT/VEGF pathways is mediated GSK3β/β-catenin signaling." (PMID 36055405, 2022). "Because LECT2 elicits the reversal of EMT, which is a prerequisite to cancer stemness." (PMID 36055405, 2022). "The functional enrichment analysis revealed that LECT2 may affect HCC progression through various pathways such as JAK/STAT signaling pathway, cell cycle, and pathways in cancer." (PMID 36160006, 2022). "c-Met is the other receptor of LECT2, and the c-Met-LECT2 protein–protein interaction (PPI) impedes MET receptor activation to inhibit vascular invasion, metastasis, proliferation, and stemness of several cancers by antagonizing different cancer activation pathways." (PMID 36969200, 2023). "Furthermore, by screening through the criteria of the PPI network, cancer-related pathway and TRS modeling, essential features with gene symbols of EPB41, PSMA1, FGFR3, MRAS, LEP, C7orf46, LOC285000, LBP, ZNF35, SLC30A3, LECT2, RNF7, and DYNC1I1 were identified as PRBs for COAD patients." (PMID 32528533, 2020). "Xu and colleagues showed that LECT2/TIE-1 signaling pathway promotes liver fibrogenesis; however, the significance of LECT2/TIE-1 in cancer is still not clear." (PMID 32604863, 2020).
infection (11 papers, 2016 to 2023). The state of being infected such as from the introduction of a foreign agent such as serum, vaccine, antigenic substance or organism. "The most prominent LECT2 is due to its potential role in fish inflammatory response during pathogenic infection." (PMID 37383149, 2023). "This was supported by infection with adenovirus encoding LECT2 (Ad-LECT2) in HCC cells." (PMID 36055405, 2022). "After infection, Ifnb1 and Ddx58 expression was significantly enhanced in Lect2-TG mice, whereas their expression was impaired in Lect2-KO mice." (PMID 35676290, 2022). "Since the findings suggest that the LECT2 protein participates in the development of inflammation, by the same reasoning, one would expect its steepness to increase with tissue superinfection and infection." (PMID 38137613, 2023). "LECT2 is a chemotactic factor attracting neutrophils to the site of infection." (PMID 34667245, 2021). "lect-2 is a chemotactic factor involved in the recruitment of neutrophils to the site of infection." (PMID 32010129, 2019). "To examine further whether LECT2 is important for innate immune responses against infection with viruses other than HCV, we infected Lect2-TG and Lect2-KO mice with lymphocytic choriomeningitis virus (LCMV) or mouse hepatitis virus (MHV) via intraperitoneal injection." (PMID 35676290, 2022). "In this study, rLECT2 treatment or Ad-LECT2 infection reduced cell viability in rat and human HCC cells but not affected the cell growth in normal hepatocytes." (PMID 36055405, 2022). "In primary human hepatocytes, LECT2 mRNA was induced by 4-5-fold following JFH-123 infection (reference data GSE31264 and GSE31455); therefore, LECT2 might be involved in the regulation of hepatitis C virus (HCV) replication and the pathogenesis of CHC." (PMID 35676290, 2022). "Eight of them (FN1, ALB, CTSL1, OTFB, LYZ, CATHL1, MMP9, LECT2) did not change their expression at the level of transcription and transcripts of 3 of them (RSFR, LYG2, CSTC) even increased following infection." (PMID 28623956, 2017).
metabolic disease (6 papers, 2017 to 2025). A congenital disorder (due to inherited enzyme abnormality) or acquired (due to failure of a metabolically important organ) disorder resulting from an abnormal metabolic process. "Although growing evidence suggests that LECT2 acts as a modulator of immune and inflammatory reactions, few studies have focused on the function of LECT2 in metabolic disorders." (PMID 28376109, 2017). "In the present study, we examined the relationship of LECT2 with TNF-α and MCP-1, which are pro-inflammatory adipokines involved in the development of metabolic diseases." (PMID 28278265, 2017).
bacterial infection (5 papers, 2012 to 2024). "LECT2 was identified as an APP during bacterial infection in zebrafish and presented an mRNA upregulation in a lice density-dependent manner in both wild and farmed Atlantic salmon skin at 24–26 dpi." (PMID 32244468, 2020). "In Asian seabass and croceine croaker, the expression of LECT2 was significantly increased in liver and spleen with bacterial infection compared to healthy fish." (PMID 31480179, 2019). "The up-regulation of fish LECT2 expression under bacterial infection has been reported in many fishes, including zebrafish with Aeromonas salmonicida, croceine croaker with Vibrio alginolyticus, asian seabass with Vibrio harveyi, lamprey with Escherichia coli." (PMID 31480179, 2019).
immune diseases (4 papers, 2016 to 2024). "This review provides an integrated perspective on the current understanding of how LECT2 is associated with immune diseases, with the aim of facilitating the development of drugs or probes against LECT2 for the theranostics of immune-related diseases." (PMID 36969200, 2023). "Because LECT2 is a cytokine that originates in the blood and has been implicated in a variety of immune disorders, our study suggests that immune signals from the blood control HSC expansion and mobilization." (PMID 27596364, 2016). "Leukocyte cell-derived chemotaxin 2 (LECT2) is linked to various immune diseases." (PMID 39206203, 2024). "Here, we provide a comprehensive summary of the structure, the “double-edged sword” function, and the extensive signaling pathways of LECT2 in immune diseases, as well as the potential applications of LECT2 in therapeutic interventions in preclinical or clinical trials." (PMID 36969200, 2023).
colorectal (2 papers, 2018 to 2024). "Therefore, we investigated whether loss of Lect2 had an effect on the inflammatory response during colorectal tumorigenesis." (PMID 30559928, 2018).
LECT2 also shares sentences with these, for which no sentence is quoted: type 2 diabetes (5 papers); Hypertension (3); infectious disease (2); inflammation (2); kidney disease (2); adenocarcinoma (1); autoimmune hepatitis (1); cardiovascular disease (1); Cholestatic liver disease (1); chronic heart failure (1); chronic Hepatitis B (1); chronic hepatitis C (1); hyperlipidemia (1); liver (1); liver cirrhosis (1); nephrotic syndrome (1); Osteopenia (1); pancreatic cancer (1); polyneuropathy (1); Renal insufficiency (1); Splenomegaly (1); stable angina (1); Stroke (1); unstable angina (1).